OPRM1 (opioid receptor mu 1)
Diseases named in the same sentence as OPRM1 in open-access papers (continued):
Sharing a sentence is not in itself a finding about the gene and the disease.
opioid use disorder (27 papers, 2018 to 2026). A substance-related disorder that involves the recurring use of opioids despite negative consequences. "Sex-differential OPRM1 DNA methylation was observed to be linked to lower opioid use disorder (OUD) cases for females (p = 0.006)." (PMID 37240556, 2023). "The OPRM1 gene rs1799971 (A118G) has been identified for its association with Opioid use disorder (OUD)." (PMID 37964305, 2023). "Variation in the OPRM1 gene (rs1799971) potentially reduces the response to buprenorphine, and the G allele associated with potentially reduced response has also been implicated as a risk allele for opioid use disorder in genome-wide association studies." (PMID 36145611, 2022). "OPRM1 SNPs rs1799971 and rs1799972 have been previously implicated in opioid use disorder." (PMID 34910759, 2021). "The possible involvement of the C allele of OPRM1’s rs73568641 in a decreased chance of opioid use and/or decreased methadone dose in females suggests the involvement of OPRM1 gene in not only opioid use disorder, but also treatment outcomes." (PMID 34910759, 2021). "Epigenetic variation of DNA methylation of the mu-opioid receptor gene (OPRM1) has been identified in the blood and saliva of individuals with opioid use disorder (OUD) and infants with neonatal opioid withdrawal syndrome (NOWS)." (PMID 33763662, 2020). "By identifying Fgf12 as a novel candidate gene and highlighting its epistatic interaction with Oprm1, this study sets the stage for a paradigm shift in our approach to opioid use disorder, from focusing solely on receptor-level pharmacology to embracing complex genetic and signaling networks." (PMID 41487078, 2026). "This association between OPRM1 rs1799971 SNP and the possibility of an increased chance of relapse in patients undergoing Naltrexone treatment for opioid use disorder in Jordanian patients was not significant (p = 0.55)." (PMID 29881439, 2018). "Two key modulators emerged: a gene on chromosome 10 called Oprm1, which codes for a well-known opioid receptor; and a gene on chromosome 16 that codes for a signaling protein called fibroblast growth factor 12 (Fgf12), which has not previously been linked to opioid use disorder." (PMID 41487078, 2026). "Additionally, OPRM1 is targeted by naltrexone, which is FDA-approved for treating AUD and opioid use disorder, and as a combination drug, naltrexone-bupropion, for the treatment of obesity Importantly, both the PDE4B and OPRM1 loci exhibited concordant effects on AUD and BMI." (PMID 38746260, 2024).
lung carcinoma (23 papers, 2012 to 2025). "The rs1799971 polymorphisms of the OPRM1 gene is related to the analgesic effect and sufentanil consumption in Chinese Han patients after radical operation of lung cancer." (PMID 32024468, 2020). "In the current study, rs6941653 in OPRM1 was further identified associated with lung cancer risk in Chinese population." (PMID 32194810, 2020). "The effects of OPRM1 SNPs on the analgesic effect and consumption of sufentanil after thoracoscopic-assisted radical resection of lung cancer were evaluated in 225 Han Chinese cancer patients." (PMID 36422103, 2022). "Finally, two variants (rs6941653 in OPRM1 and rs402969 in NLRP8) were identified as novel susceptibility loci of lung cancer in Chinese population." (PMID 32194810, 2020). "For the first time, our study evaluated the correlation between SNPs at the rs1799971, rs563649 and rs1323040 loci in OPRM1 and the rs2032582, rs1045642 and rs1128503 loci in ABCB1 with sufentanil consumption in Chinese Han patients who underwent radical resection of lung cancer." (PMID 30455395, 2019). "Our results showed that the SNPs of rs1799971 locus in OPRM1 gene were significantly correlated with the consumption of PCEA sufentanil, rather than post-operative side effects in patients who underwent radical resection of lung cancer." (PMID 30455395, 2019). "Our study is the first to evaluate the correlation between SNPs at the rs1799971, rs563649 and rs1323040 loci in the OPRM1 gene and the rs2032582, rs1045642 and rs1128503 loci in the ABCB1 gene with sufentanil consumption in Chinese Han patients who underwent radical resection of lung cancer." (PMID 30455395, 2019).
breast carcinoma (22 papers, 2014 to 2025). "Despite the potential role of the opioid system in memory functions, the effects of SNPs in OPRM1 (gene encoding the Mu-opioid receptor) on cognitive function in breast cancer patients have been rarely explored." (PMID 36123640, 2022). "The relationship between OPRM1 methylation and increased breast cancer risk is based on the results of population epidemiological studies." (PMID 35024367, 2021). "We found that soybean intake reduced the risk of breast cancer (OR = 0.500, 95%CI: 0.291–0.859) and that low soybean intake combined with OPRM1 hypermethylation increased the risk of breast cancer (OR = 5.592, 95%CI: 2.905–10.764)." (PMID 35024367, 2021). "Strikingly, we also found that regular sport is associated with a decreased OPRM1 methylation level in breast cancer tissues (OR = 0.624, 95%CI: 0.399–0.976)." (PMID 35024367, 2021). "This study identified that OPRM1 hypermethylation in PBL DNA is correlated with increased risk of breast cancer." (PMID 35024367, 2021). "A combination of low vegetable, garlic, poultry, and milk intake and high pork intake and OPRM1 hypermethylation in PBL DNA was observed in our study to be significantly associated with an increased risk of breast cancer (P < 0.05)." (PMID 35024367, 2021). "In this study, we discovered for the first time a series of valuable associations between OPRM1 methylation and breast cancer." (PMID 35024367, 2021). "We examined the association between the recurrent breast cancer and genotypes of OPRM1 A118G SNP (AA vs. AG vs. GG) in Korean women population." (PMID 33173414, 2020). "Herein, we investigated the association between A118G OPRM1 gene polymorphism and breast cancer risk." (PMID 25618602, 2015). "Association of OPRM1 methylation in peripheral blood leukocyte DNA and breast cancer risk." (PMID 35024367, 2021). "By inference, less sports and hypermethylation of OPRM1 may have combined action on the inhibition of endogenous opioid substances and increased the risk of breast cancer." (PMID 35024367, 2021). "Additionally, we found that high psychological stress combined with OPRM1 hypermethylation in PBL DNA increased the breast cancer risk with a strong correlation (OR = 5.340, 95%CI: 2.634–10.829)." (PMID 35024367, 2021). "First, we found that OPRM1 hypermethylation in PBL DNA increased the breast cancer risk." (PMID 35024367, 2021). "Consequently, OPRM1 G allele presence at that site is a highly significant risk factor in breast cancer development." (PMID 25618602, 2015). "In conclusion, since the MOR G allele (40D variant) proves more sensitive to endogenous opioid peptides and promotes the recently reported estrogen receptor interaction, our results highlight the significance of the OPRM1 G allele as a serious risk factor in breast cancer development." (PMID 25618602, 2015). "Furthermore, OPRM1 hypermethylation combined with low intake of vegetable, garlic, soybean, poultry, and milk; less regular sports; and a high pork intake and high psychological stress index significantly increased the risk of breast cancer." (PMID 35024367, 2021). "Genetic polymorphisms in the mu-opioid receptor (OPRM1) and catechol-o-methyltransferase (COMT) genes have been shown to increase breast cancer risk." (PMID 35198317, 2022). "In our study, the genetic polymorphisms of OPRM1 and COMT affected the overall survival of breast cancer patients." (PMID 35198317, 2022). "The genetic polymorphisms of OPRM1 and COMT affected the overall survival of breast cancer patients, in concordance with previous research." (PMID 35198317, 2022). "In the present study, OPRM1 and COMT polymorphisms demonstrated a prognostic impact in breast cancer, significantly affecting overall survival at 30 years." (PMID 35198317, 2022). "Relationship between environmental factors exposures and OPRM1 methylation in breast cancer tissue DNA." (PMID 35024367, 2021).
breast carcinoma (continued). "By adjusting the marital status, educational level, occupation, and family history of cancer, we found a significant association between the hypermethylation of OPRM1 in PBL DNA and the risk of breast cancer (OR = 1.914, 95%CI = 1.357–2.777, P = 0.000)." (PMID 35024367, 2021). "In addition, we also found a significant combination of OPRM1 hypermethylation and a high pork intake (≥1 time/week, OR = 3.628, 95%CI: 1.593–8.262, P = 0.000) and high psychological stress index (>15, OR = 5.340, 95%CI: 2.634–10.829, P = 0.000) for increased breast cancer risk." (PMID 35024367, 2021). "Combined and interactive effects between OPRM1 methylation and environmental factors in breast cancer." (PMID 35024367, 2021). "A healthy diet with sufficient intake of vegetable, garlic, soybean, poultry and milk; a low pork intake; regular sports and healthy psychosocial adaptability is very beneficial for breast cancer prevention, especially for OPRM1 hypermethylation carriers." (PMID 35024367, 2021). "We investigated the impact of OPRM1 A118G SNP on breast cancer recurrence in Korean adult female patients." (PMID 33173414, 2020). "Firstly, the effect of the G allele on intraoperative haemodynamic parameters and postoperative pain should be assessed to confirm the relevance of OPRM1 A118G SNPs to breast cancer recurrence." (PMID 33173414, 2020). "The aim of this retrospective study was to assess the potential link between OPRM1 A118G SNP and breast cancer recurrence." (PMID 33173414, 2020). "μ-Opioid receptors, the product of the OPRM1 gene, have been demonstrated on several cancer cell lines including breast cancer, non-small cell lung cancer, adenocarcinoma and gastric carcinoma." (PMID 30229370, 2018). "OPRM1 hypermethylation in PBL DNA combined with low intake of vegetable, garlic, soybean, poultry, and milk; high pork intake; less regular sports and a high psychological stress index significantly increased the risk of breast cancer." (PMID 35024367, 2021). "Personalized treatment considering the correlation between OPRM1 hypermethylation and ER and PR status may provide a novel benefit for breast cancer patients." (PMID 35024367, 2021). "Thus, we suggest that individuals with OPRM1 hypermethylation in PBL DNA maintain a good psychological state to prevent breast cancer." (PMID 35024367, 2021). "Therefore, this study was carried out to investigate the relationship of OPRM1 methylation in PBL DNA, environmental factors, and their combinations and interactions with breast cancer risk." (PMID 35024367, 2021). "Targeted induction of OPRM1 methylation to regulate gene expression and design of possible therapeutic drugs may provide a novel remedy for breast cancer patients." (PMID 35024367, 2021). "Therefore, we also encourage that women with OPRM1 hypermethylation should increase their intake of vegetable, garlic, milk and poultry and reduce their intake of pork to prevent breast cancer." (PMID 35024367, 2021). "Additionally, OPRM1 A118G SNPs have been reported to affect tumour growth and progression in breast cancer patients." (PMID 33173414, 2020). "We examine the association of the most frequent MOR (A118G) gene polymorphism on breast cancer risk in a Northeastern Polish population by PCR-RFLP comparison of A and G allele frequency at OPRM1 gene A118G polymorphic site in breast cancer-diagnosed patients with healthy control group frequencies." (PMID 25618602, 2015). "However, the relationship between OPRM1 methylation and breast cancer risk has not been reported yet." (PMID 35024367, 2021). "In particular, comparing with the individuals of OPRM1 hypomethylation in PBL DNA and regular sports, we found that less frequent sports (<1 time/week) combined with OPRM1 hypermethylation in PBL DNA increased breast cancer risk with a strong association (OR = 4.114, 95%CI: 2.357–7.181)." (PMID 35024367, 2021).
breast carcinoma (continued). "The interpretation that the observed epigenetic associations with the development of persistent pain after breast cancer surgery have to be attributed to the global methylation not reflecting a specific regulation in OPRM1 is unlikely to change if more than six CpG sites in OPRM1 were analyzed." (PMID 31775878, 2019). "In conclusion, neither the presence of OPRM1 A118G SNPs nor the anaesthetic technique used during breast cancer surgery had an effect on breast cancer recurrence in Korean adult patients." (PMID 33173414, 2020). "DNA methylation was quantified from d = 6, 4, or 4 CpG sites located in OPRM1, TLR4, and LINE1, respectively, in n = 70 patients with persistent pain and in n = 70 patients assigned to the “non-persistent pain” phenotype group based on the 3-year follow-up data after breast cancer surgery." (PMID 31775878, 2019). "Personalized promotion on regular sports and soybean intake and precision treatment based on DNA methylation markers (OPRM1) should be encouraged with the consideration of the correlation between OPRM1 hypermethylation and ER/PR, HER-2 negative status in breast cancer." (PMID 35024367, 2021).
substance dependence (22 papers, 2005 to 2025). The psychological or physiological need to take a substance in order to experience its effects or to avoid the effects of its absence. "rs648893 (C/T) polymorphism an Intronic SNP of the OPRM1 gene that implicated in DNA splicing has been recently nominated as candidate for substance dependence including drugs." (PMID 33402148, 2021). "OPRM1 is associated with substance dependence which supports the notion that this gene is related to TD." (PMID 29649967, 2018). "A single study cannot confirm the correlation between OPRM1-A118G polymorphism and nicotine-dependence risks convincingly." (PMID 29137427, 2017). "More than 100 SNPs in the human OPRM1 gene have been identified, some of which have been tested for associations with a range of substance dependence." (PMID 16887046, 2006). "The gene encoding the mu-opioid receptor (OPRM1) is reported to be associated with a range of substance dependence." (PMID 16887046, 2006). "Even though the association of the A118G OPRM1 variant with specific substances is debatable, a collaborative meta-analysis (n = 28,689 subjects with European ancestry) indicated that the G allele had a protective effect on general substance dependence (OR = 0.90; 95% CI: 0.83–0.97)." (PMID 30804861, 2019). "It has been demonstrated that OPRM1 was related to substance dependence and drug dependence." (PMID 32009227, 2020). "The binding of β-endorphin to μ-opioid receptors (genetic locus OPRM1) might reinforce nicotine dependence by increasing dopamine actions in reward centers." (PMID 29137427, 2017). "This region harbors OPRM1, a candidate gene for substance dependence." (PMID 16451620, 2005).
neuroblastoma (19 papers, 2012 to 2025). Neuroblastoma (NB) is the most common solid, extracranial childhood tumor. "In particular, overexpression of Sox18 can stimulate MOR gene transcription in human and murine neuroblastoma cells, suggesting that Oprm1 is a downstream target of Sox18 protein." (PMID 36233105, 2022).
heroin addiction (18 papers, 2014 to 2026). "The MOR is encoded by the OPRM1 gene, which has been intensively studied in heroin addiction and other opioid addictions, as well as in methadone and buprenorphine-based treatments for drug addiction." (PMID 40993075, 2025). "The involvement of mu opioid receptor in addiction is supported by reports that genetic mutations in OPRM1 increased vulnerability of heroin addiction in humans and in preclinical models." (PMID 35548327, 2021). "Recently, we identified a heroin addiction severity-associated intronic SNP that modulates alternative splicing of the human OPRM1 variants via hnRNPH interaction." (PMID 25343478, 2014). "Furthermore, the human intronic SNP rs9479757 in OPRM1 was associated with heroin addiction severity and decreased binding affinity of HNRNPH1, resulting in exon 2 skipping." (PMID 26658939, 2015). "Another study in heroin addicts found, however, that the OPRM1 promoter was also hypermethylated, with increased density around the Sp1 transcription factor binding site, directly inhibiting the binding of the transcriptional machinery." (PMID 41596476, 2026). "Additional systems biology results indicated heroin dependence as the highest-risk manifestation linked to these genes, and PGx analyses suggested DRD1, DRD2, BDNF, and OPRM1 as promising targets for future studies." (PMID 41333412, 2025). "Our findings revealed that the OPRM1 gene may be implicated in drug addiction among Jordanians, in particular the functioning SNP (rs1799971) found to be significantly associated with drug addiction which is in consistence with a Chinese study on336 Han heroin addicts." (PMID 33402148, 2021). "Association studies on OPRM1 A118G and methadone response have been conducted in methadone maintenance treatment (MMT) settings for the treatment of heroin dependence, however the influence of this SNP on MMT outcome remains unclear." (PMID 38341456, 2024). "Moreover, there is some direct evidence that there are genes related to both heroin dependence and morphine dependence, such as OPRM1." (PMID 33328875, 2020). "This study used the completion/incompletion of MMT as the compliance index and the negative rate of urine morphine test as the curative effect index, recruited heroin addicts from Shanghai as research objects, and studied the impact of the ABCB1/OPRM1 gene SNPs on the MMT curative effect." (PMID 30420869, 2018).